HDAC3 (histone deacetylase 3)
Diseases named in the same sentence as HDAC3 in open-access papers (continued):
Sharing a sentence is not in itself a finding about the gene and the disease.
brain injury (3 papers, 2020 to 2025). Acute and chronic (see also brain INJURIES, CHRONIC) injuries to the brain, including the cerebral hemispheres, CEREBELLUM, and brain STEM. "A previous study has shown that HDAC3 expression is up-regulated in neurons after traumatic brain injury (TBI) in SD rats, and our study has seen the same results." (PMID 40584448, 2025). "It has been shown that HDAC3 expression increased in brain neurons of traumatic brain injury (TBI)." (PMID 32190700, 2020).
breast tumors (3 papers, 2018 to 2022). "For example, class I HDACs have been found to be overexpressed in bladder tumors, breast tumors, prostate tumors, and renal cells, and overexpression of HDAC2 and HDAC3 has also been shown to be associated with clinicopathological indicators of disease progression." (PMID 36371227, 2022). "Previous studies have shown that HDACs are overexpressed in ER-α positive breast tumors, and HDAC1, HDAC3 and HDAC6 protein expressions correlate with ER-α expression." (PMID 30352569, 2018).
Burkitt lymphoma (3 papers, 2019 to 2021). A rare form of malignant mature B-cell non-Hodgkin lymphoma. "Knocking down HDAC3 can also up-regulate the expression of miR-101, so there is a negative correlation between the expression of HDAC3 and miR-101 in Burkitt lymphoma cells." (PMID 34658308, 2021). "qRT-PCR was performed to determine the expression of TCF3, histone deacetylase 3 (HDAC3), and microRNA-101 (miR-101) in the Burkitt lymphoma (BL) tumor tissues and lymph node tissues with reactive lymph node hyperplasia (RLNH)." (PMID 34658308, 2021). "So far, it can be seen that the highly expressed transcription factor TCF3 in Burkitt lymphoma can recruit HDAC3 in the miR-101 promoter region, inhibit miR-101 expression, and regulate the activity of the Akt/mTOR pathway, thereby improving the biological performance of Burkitt lymphoma cells." (PMID 34658308, 2021). "The ability of EBNA1 to interfere with HDAC3 was also evident in Burkitt lymphoma cells." (PMID 32273550, 2020).
diabetic cardiomyopathy (3 papers, 2017 to 2023). Diabetic cardiomyopathy is a disorder of the heart muscle in people with diabetes. "It would be interesting to see, if NCoR1 gene silencing could rescue diabetic cardiomyopathy in these mice by inactivating HDAC3 enzymatic activity." (PMID 37674539, 2023). "Moreover, suppression of Hdac3 has been elucidated to prevent diabetic cardiomyopathy in mouse models through epigenetic regulation of the DUSP5-ERK1/2 pathway." (PMID 33240312, 2020).
endometrial cancer (3 papers, 2022 to 2025). Primary or metastatic malignant neoplasm involving the endometrium (mucous membrane that lines the endometrial cavity). "In endometrial cancer, Histone Deacetylase 3 (HDAC3) plays a pivotal role in promoting tumor growth by repressing STING expression through epigenetic mechanisms." (PMID 39949780, 2025). "This is the first study to demonstrate that the STING pathway is inhibited in endometrial cancer, laying groundwork for treating endometrial cancer by combining STING agonists and HDAC3 inhibitors." (PMID 36230643, 2022). "Herein, HDAC3 inhibitors were found to significantly up-regulate the expression of STING, revealing that HDAC3 is a key acetylated regulatory enzyme that regulates STING expression in endometrial cancer." (PMID 36230643, 2022). "Therefore, this study uncovers a novel molecular mechanism by which HDAC3 inhibits STING transcription via β-estradiol-ERα, and provides a promising therapy with a combination of HDAC and STING for combating endometrial cancer." (PMID 36230643, 2022).
Friedreich ataxia (3 papers, 2018 to 2025). An inherited condition that affects the nervous system and causes movement problems. "PD106 and RGFP109 are two drugs developed to target Friedreich’s ataxia, which also have good selective potency for HDAC3." (PMID 37072432, 2023). "This compound has a Ki value of 14 nM for HDAC3, which was 10 times lower than the Ki for HDAC1, while its analog, RGFP109, which is also used as a promising treatment for Friedreich’s ataxia, shows a better potency for HDAC3 with the Ki value of 5 nM, and 32 nM for HDAC1." (PMID 29498635, 2018). "Recently, HDAC3 inhibitors have been proved to suppress degeneration and improve behavioral performance in multiple neurodegenerative conditions, including Parkinson’s disease (PD), Alzheimer’s disease (AD), Friedreich’s ataxia, spinal cord injury, and ischemic stroke." (PMID 37072432, 2023).
glaucoma (3 papers, 2013 to 2025). Increased pressure in the eyeball due to obstruction of the outflow of aqueous humor. "Specifically, HDAC3 inhibition is critical for regulating RGC atrophy and has been shown to promote neuron regeneration, which was confirmed by higher RGC density and restoration of optic nerve axon morphology in an experimental rabbit glaucoma model after treatment with the p-DMB + P + R system." (PMID 41157282, 2025).
hypothyroidism (3 papers, 2021 to 2023). Abnormally low levels of thyroid hormone. "It would be a reasonable approach to inhibit the enzymatic activity of HDAC3 to rescue the impairments induced by hypothyroidism." (PMID 35887216, 2022). "Our data demonstrate the pivotal role of HDAC3 in cerebellar developmental defects by hypothyroidism in vivo." (PMID 35887216, 2022). "The HDAC3 inhibitor might serve as a novel therapeutic agent for hypothyroidism-induced cerebellar defects by acetylating histone tails and stimulating transcription at thyroid hormone-responsive gene loci." (PMID 35887216, 2022). "Therefore, it is highly likely that the enzymatic activity of HDAC3 is responsible for the cerebellar developmental defects in hypothyroidism." (PMID 35887216, 2022).
idiopathic pulmonary arterial hypertension (3 papers, 2020 to 2023). A sporadic form of pulmonary arterial hypertension (PAH) characterized by elevated pulmonary arterial resistance leading to right heart failure. "HDAC3 inhibition can significantly promote SOD3 expression which is beneficial to the alleviation of idiopathic pulmonary arterial hypertension (IPAH)." (PMID 37072432, 2023). "Inhibition of HDAC3 significantly promoted SOD3 expression and benefited the alleviation of idiopathic pulmonary arterial hypertension (IPAH)." (PMID 37759978, 2023). "Comprehensive analysis of expression and regulation of class I HDACs (HDAC1, HDAC2, HDAC3 and HDAC8) was performed in cardiopulmonary tissues and adventitial fibroblasts isolated from pulmonary arteries (PAAF) of idiopathic pulmonary arterial hypertension (IPAH) patients and healthy donors." (PMID 32733053, 2020).
lung diseases (3 papers, 2020 to 2024). "The functions of HDAC3 in pulmonary diseases are gradually being elucidated." (PMID 39224841, 2024).
medulloblastoma (3 papers, 2014 to 2022). A malignant, invasive embryonal neoplasm arising from the cerebellum. "LSD1, HDAC2, and HDAC3 are key targets for 4SC-202, and thus upregulation of these targets across the studied medulloblastomas makes 4SC-202 a more actionable therapeutic." (PMID 29099739, 2017).
myocardial infarction (3 papers, 2021 to 2025). Gross necrosis of the myocardium, as a result of interruption of the blood supply to the area, as in coronary thrombosis. "I/R-induced TUG1 binds to miR-132-3p to activate histone deacetylase 3 and then provokes intracellular reactive oxygen species accumulation, and worsens the injury of acute myocardial infarction." (PMID 34429073, 2021). "The molecular mechanism is closely related to Histone Deacetylase 3 (HDAC3), a crucial element of the circadian negative feedback loop, which upregulates BMAL1 to restore mitochondrial autophagy by regulating the REV-ERBα/BMAL1 pathway, thereby alleviating myocardial infarction injury." (PMID 40429770, 2025).
psoriasis (3 papers, 2021 to 2025). An autoimmune condition characterized by red, well-delineated plaques with silvery scales that are usually on the extensor surfaces and scalp. "Increased expression of HDAC3 isoform mRNA in keratinocytes is observed in patients with psoriasis." (PMID 40943548, 2025). "Thus, inhibition of HDACs, in particular the HDAC3 isoform, alleviates mitochondrial dysfunction in psoriasis and impairs cytosolic DNA sensing and downstream signaling pathways." (PMID 40943548, 2025). "Although the effect of HDAC3 has not been studied in PsA specifically, HDAC3 inhibitors were suggested by some authors as potential future drugs for inflammatory diseases, including RA and psoriasis." (PMID 33869291, 2021). "However, it has also been found that the activities of HDAC1, HDAC2, and HDAC3 in psoriatic lesions are not significantly different from those in healthy controls, which might be related to the different severities of psoriasis in patients included in different groups of the study." (PMID 38008779, 2023).
rectal cancer (3 papers, 2021 to 2024). A primary or metastatic malignant neoplasm that affects the rectum. "RSV and leucotaxol elevate PD-L1 expression in rectal cancer through NF-κB signaling mediated by histone deacetylase 3 (HDAC3)/p300, enhancing rectal cancer cell apoptosis." (PMID 39439517, 2024). "Because the expression of HDAC3 was greatly upregulated in colon and rectal cancers, we investigated the role of HDAC3 in these cancers." (PMID 38805168, 2024). "To this end, we performed GO analysis of genes showing a positive correlation between their expression level and the HDAC3 expression level in colon and rectal cancers." (PMID 38805168, 2024). "Previous studies have suggested that HDAC3 accelerates the progression of colon and rectal cancers." (PMID 38805168, 2024). "Taken together, these findings show that TIP60 is downregulated in various cancers, including colon and rectal cancers, and TIP60 regulates the expression of HDACs, particularly as a transcriptional repressor of HDAC3 in HCT116 cells." (PMID 38805168, 2024).
Rett syndrome (3 papers, 2013 to 2019). A severe neurodevelopmental disorder affecting the central nervous system.
sarcoma (3 papers, 2009 to 2024). A usually aggressive malignant neoplasm of the soft tissue or bone. "The previous results showed that the expression of class I HDACs, including HDAC1, HDAC2, and HDAC3, is associated with a poor prognosis of patients with sarcoma." (PMID 33637599, 2021). "We found that the mRNA expression of HDAC class I genes HDAC1, HDAC2 and HDAC3 was associated with prognosis in sarcoma." (PMID 33637599, 2021). "We analyzed the TCGA public database of 263 STS samples (cBioPortal.org) to identify the potential role of HDACs in sarcoma and observed an association between higher expression of class I HDACs, including HDAC1, HDAC2 and HDAC3 with shorter overall survival (p<0.001)." (PMID 33637599, 2021). "Since class I HDACs affect cell proliferation, we also detected the expression of HDAC1, HDAC2, and HDAC3 after treatment with chidamide and founded inhibited expression of HDAC1, HDAC2, and HDAC3 in the three sarcoma cell lines." (PMID 33637599, 2021). "Therefore, we hypothesized that our observations on MS-275 (killingsynovial sarcoma cells, but activating NF-κB in a manner which can be blocked with 17-AAG)might be explained specifically by HDAC3 inhibition." (PMID 19325926, 2009).
subarachnoid hemorrhage (3 papers, 2020 to 2024). A serious neurological disorder characterized by intracranial hemorrhage into the subarachnoid space. "NF-κB also regulates histone deacetylase 3 (HDAC3) expression, and MSC-Exos inhibit p65 phosphorylation, NF-κB transcriptional activity, HDAC3 expression, and neuroinflammation in subarachnoid hemorrhage." (PMID 38372822, 2024). "The researchers also found that targeted delivery of miR-193b-3p into the brain following subarachnoid hemorrhage reduced neuroinflammation and attenuated neuronal degeneration by inhibition of the HDAC3/NF-κB signaling pathway." (PMID 32545705, 2020).
adenoma (2 papers, 2013). A neoplasm arising from the epithelium. "We performed a PCR array for HDAC1, HDAC2, HDAC3, HDAC5 and HDAC7 on human rectal biopsies from patients with or without an adenoma in the colon (n = 86 subjects total)." (PMID 23724067, 2013).
age-related macular degeneration (2 papers, 2023 to 2025). Age-related loss of vision in the central portion of the retina (macula), secondary to retinal degeneration. "Additionally, disease-relevant connections have been identified: in both mouse models and patient tissues of age-related macular degeneration (AMD), reduced levels of IPMK result in impaired HDAC3 activation, disrupted gene regulation, and increased proteostatic stress." (PMID 41008573, 2025).
alcohol dependence (2 papers, 2019 to 2021). Physical and psychological dependence on alcohol. "It is worth noting that HDAC3 mediated physiology and behavioural mal‐adaptions of alcohol dependence in rat44; HDAC3 was involved in the chronic alcohol‐binge mediated liver injury." (PMID 33973278, 2021).
amyloid (2 papers, 2017 to 2022). "Inhibition of HDAC3 in the hippocampus attenuates spatial memory deficits, as indicated in the Morris water maze test, and decreases amyloid plaque load and Aβ levels in the brains of APP/PS1 mice." (PMID 28771976, 2017). "Here, our data provide the first evidence that the inhibition of HDAC3 by lentivirus‐mediated shRNA in the hippocampus attenuates spatial memory deficits and decreases amyloid plaque load and Aβ levels in 9‐month‐old APP/PS1 mice." (PMID 28771976, 2017). "Our results also demonstrate that inhibition of HDAC3 in the hippocampus of APP/PS1 mice decreases Aβ levels and alleviates amyloid plaque formation, which might be associated with decreased PS‐1 levels." (PMID 28771976, 2017). "In conclusion, our data show that inhibition of HDAC3 ameliorates spatial memory impairment and improves AD‐related neuropathogenesis, while HDAC3 overexpression increases the amyloid burden in AD mice, which suggests that inhibition of HDAC3 is a potential therapy for the treatment of AD." (PMID 28771976, 2017).
anaphylaxis (2 papers, 2018 to 2019). An acute hypersensitivity reaction that occurs from exposure to an allergen. "Roles of TGaseII, SOCS1, COX-2, and HDAC3 in allergic inflammation, such as anaphylaxis, have been previously reported." (PMID 30459600, 2018). "Further studies are needed to identify molecules regulated by HDAC3 for a better understanding of cellular interactions mediated by HDAC3 and MCP1 during anaphylaxis." (PMID 31597362, 2019). "Small molecules that fit with the structure of the HDAC3 protein could be developed as drugs targeting PCA and PSA, and food-induced systemic anaphylaxis." (PMID 31597362, 2019). "Roles of microRNAs that form negative feedback loops with hallmarks of anaphylaxis such as HDAC3 in anaphylaxis and cellular interactions will also be discussed." (PMID 31597362, 2019).
astrocytoma (2 papers, 2008 to 2020). "For class I, the highest median value observed was 2.87 (HDAC8 in low-grade astrocytoma) and the lowest median value was 0.62 (HDAC3 in astrocytoma grade III)." (PMID 18713462, 2008).
atrial fibrillation (2 papers, 2021 to 2025). A disorder characterized by an electrocardiographic finding of a supraventricular arrhythmia characterized by the replacement of consistent P waves by rapid oscillations or fibrillatory waves that vary in size, shape and timing and are accompanied by an irregular ventricular response. "In summary, although HDAC1 and HDAC3 are involved in the development of calcium management defects associated with atrial fibrillation, class IIa HDACs such as HDAC5 and HDAC7 provide protection from dysfunction caused by tachypacing." (PMID 40660005, 2025). "The cardiomyocyte dysfunction of atrial fibrillation is further attributed to over-expression of Class I HDAC3." (PMID 33549119, 2021).
autism (2 papers, 2021). Persistent deficits in social interaction and communication and interaction as well as a markedly restricted repertoire of activity and interest as well as repetitive patterns of behavior. "To identify potential epigenetic aberrations in the VPA-induced autism model, we examined the levels of class I HDACs (HDAC1, HDAC2, HDAC3, and HDAC8) and AcH3 in the PFC nuclear fraction." (PMID 33994921, 2021).
chronic lymphocytic leukaemia (2 papers, 2017 to 2021). "Furthermore, the MYC-mediated miR-29 repression mechanism for the therapy of aggressive B-cell malignancies (B-cell malignancies is the synonym of chronic lymphocytic leukemia according to Medical Subject Headings (MeSH)) by applying the HDAC3 and EZH2 as therapeutic targets was reported." (PMID 28340554, 2017). "Furthermore, HDAC3 can catalyse the deacetylation of the Notch1 intracellular domain (NICD1), thereby promoting NICD1 protein stability, which is involved in the progression of T cell acute lymphoblastic leukaemia (ALL) and chronic lymphocytic leukaemia (CLL)." (PMID 34395273, 2021).
colorectal adenocarcinoma (2 papers, 2013 to 2025). The most common type of colorectal carcinoma. "Recently, resistance to the HDAC-inhibitor SAHA has been reported not to be accompanied by elevated expression of HDAC1 and HDAC3 in human colorectal adenocarcinoma cells." (PMID 23372654, 2013).
dementia (2 papers, 2023 to 2025). Loss of intellectual abilities interfering with an individual's social and occupational functions. "The benefits of NT3 were reported in treating memory deficits, indicating its potential in inherited and acquired forms of dementias, which revealed that the pharmacological inhibition of HDAC3 increased BDNF expression and the potential role of NT3 in AD treatment using an NT3-transduced graft." (PMID 40732937, 2025). "Moreover, we found increased HDAC3 levels, concomitantly with diminished H3 acetylation, in postmortem cortex of AD patients at Braak stages III–IV, which was associated with CDR of 0.5 and very mild dementia." (PMID 37358017, 2023).
esophageal squamous cell carcinoma (2 papers, 2022 to 2024). Esophageal squamous cell carcinoma (ESCC) is a type of esophageal carcinoma (EC) that can affect any part of the esophagus, but is usually located in the upper or middle third. "Herein, we aimed to unravel the functional role of HDAC3 in a lethal disease, esophageal squamous cell carcinoma (ESCC)." (PMID 35578338, 2022). "In esophageal squamous cell carcinoma (ESCC), SOX4 cooperates with EZH2 and HDAC3 to enhance tumor cell progression and metastasis through epigenetic silencing of miR-31 by H3K27me." (PMID 38331879, 2024).